SFRP2 (secreted frizzled related protein 2)
Diseases named in the same sentence as SFRP2 in open-access papers (continued):
Sharing a sentence is not in itself a finding about the gene and the disease.
cancer (118 papers, 2007 to 2026). A tumor composed of atypical neoplastic, often pleomorphic cells that invade other tissues. "eCAFs also strongly expressed cancer-associated genes including tumorigenesis SFRP2 (Secreted frizzled-related protein 2) and proteoglycan LUM (Lumican)." (PMID 35742914, 2022). "Cluster 0 and 6 were enriched in cells expressing genes related to cell cycle and cancer-associated proliferation (SFRP2, CENPF, TOP2A, UBE2C, CRABP2, MYC)." (PMID 33771987, 2021). "Lastly, some genes (HMGN5, IRS1, PHGDH, MXRA5, GOLIM4, and SFRP2) are associated with the development of multiple cancer types." (PMID 33924951, 2021). "Secreted frizzled-related protein 2 (sFRP2) is a secreted protein associated with cancer drug resistance and metastasis." (PMID 30944668, 2019). "For example, activation of canonical Wnt/ß-Catenin pathway which is implicated in almost all types of cancers, has often been attributed to epigenetic silencing of Wnt inhibitors like SFRP2 and DKK1." (PMID 24947038, 2014). "Our results showed that DNA methylation of SFRP1 and SFRP2 might be useful to predict cancer risk of surrounding normal mucosa." (PMID 28533824, 2017). "Therefore, sFRP2, which is associated with the progression and metastasis of cancer, could be a useful biomarker for its diagnosis and prediction." (PMID 30944668, 2019). "The aim of this study is to evaluate the relationship between the methylation and expression of APC, SFRP1, SFRP2, SFRP4, and SFRP5 genes involved in the Wnt signaling pathway and the risk of cancer development in IBD." (PMID 40521787, 2025). "Studies have shown that SFRP2, as an antagonist of the Wnt signaling pathway, has significantly decreased expression in a variety of cancers." (PMID 41280939, 2025). "SFRP2 shows progressive overexpression during the process from healthy individuals to benign individuals and then to cancer individuals." (PMID 41280939, 2025). "Nevertheless, there are limited studies investigating the potential of SFRP2 methylation as a predictor for other cancer outcomes, such as response to therapy or recurrence in other biological and less invasive tissues." (PMID 38802858, 2024). "Further studies are needed to fully elucidate the mechanisms underlying these effects and to determine the potential clinical implications of SFRP2 as a therapeutic target in cancer therapy." (PMID 38802858, 2024). "In our study, we characterized the expression and DNA methylation levels of SFRP2 in whole blood, adipose tissue, and colonic tissues, considering different cancer outcomes." (PMID 38802858, 2024). "TET1 potently inhibited canonical Wnt/β‐catenin signalling by demethylating and upregulating two upstream antagonists of this pathway, SFRP2 and DKK1, which was associated with inhibition of EMT and cancer cell metastasis." (PMID 37994489, 2024). "The inactivation of SFRP2 in CAFs impairs the induction of cancer cell migration and invasion and weakens the tumorigenicity of cancer cells in vivo." (PMID 38069266, 2023). "We labeled cell types as endothelial cell (Endothelial, gene expression of PLVAP, KDR, PTPRB) and cancer associated fibroblasts cell (CAFs, gene expression of FAP, MMP11, PDGFRB, SFRP2, PDGFRA, ADAMTS2)." (PMID 37065499, 2023). "The 5 members of the M0-ECM signature, FN1, VCAN, COL11A1, SFRP2, and MXRA5, have been associated with cancer progression, through markers of prognosis or the process of metastasis." (PMID 37188691, 2023). "The modulatory activity of SFRP2 is still unclear and, therefore, represents a potential target for understanding its role in cancer progression." (PMID 36552843, 2022). "Heatmap analysis showed that some oncogenes and tumor suppressor genes are shared by multiple cancer types, such as SFRP2, while the others are specific to one or very few cancers." (PMID 35931322, 2022). "The more novel findings in this study were in genes (ARID5B, BAZ2B, RABGAP1, SFRP2, and WBP1L) that are associated with cancer risk and cellular differentiation." (PMID 36685876, 2022).
cancer (continued). "As the SFRP2 promoter is hypermethylated in many cancer cells, including PC3 cells, we created PC3 cells that stably overexpress SFRP2 by utilizing the Sleeping Beauty transposon system." (PMID 36552843, 2022). "Some SASP components including WNT16B and SFRP2 display strong capacity in conferring resistance to cancer cells." (PMID 36202915, 2022). "The results of differential gene expression analysis and in vitro experiments implicate that SFRP2 is one of the key elements leading to the adaptation of cancer cells in the metastatic bone microenvironment." (PMID 36552843, 2022). "This suggests that KIF5B and SFRP2 have great potential to be early biomarkers that are consistently expressed in both cancer mouse models and clinical samples." (PMID 36002889, 2022). "Evasion of osteomimicry property of cancer cells by inhibiting SFRP2 is a possible mechanism to suppress bone metastasis." (PMID 36552843, 2022). "SFRP2 has key characteristics of matricellular proteins and has been suggested as a candidate therapeutic target in cancer." (PMID 33670920, 2021). "Many studies have investigated SFRP2 downregulation by promotor hypermethylation in several types of cancer." (PMID 33140138, 2021). "In our study, we found that SFRP2 knockdown promoted sphere formation and expression of cancer stemness markers, while overexpression of SFRP2 reduced sphere formation and expression of cancer stemness markers." (PMID 34852024, 2021). "Epigenetic downregulation of secreted frizzled-related proteins and SFRP4 by promoter methylation has been described in some cancer types however in GC this seems to be restricted to the SFRP2 gene." (PMID 33277667, 2021). "The implication of modifications in adipose tissue SFRP2 expression for chronic diseases such as cancer requires further studies, however." (PMID 30884788, 2019). "SASP factors including WNT16B and SFRP2 have remarkable potential in conferring resistance to cancer cells." (PMID 30333494, 2018). "When expression levels of the various SFRPs were correlated to each other and averaged across cancers, we found SFRP2 and 4 expression to be tightly correlated." (PMID 28218291, 2017). "Our meta-analyses further studied the OR of SFRP2 methylation between cancer samples and benign mucosal lesions, which the previous meta-analyses did not." (PMID 27659069, 2016). "Despite the apparent similar roles of SFRP1 and SFRP2 proteins, the significance of SFRP2 silencing in human cancers is generally less clear." (PMID 26337424, 2016). "GSK3β and SFRP2 are important effectors of numerous miRNAs in human cancers, so we need to further explore the biological effects of miR-224 on GSK3β and SFRP2 in a reverse logic." (PMID 26822534, 2016). "As a control, such treatment reactivated expression of SFRP1 and SFRP2 genes known to be silenced by methylation in various types of cancers." (PMID 27626696, 2016). "The dysregulation of sFRP2 has been reported in several malignancies, however the mechanisms by which it contributes to the biology of these cancers has been variable." (PMID 27821163, 2016). "The findings of cancer studies suggest that sFRP2 acts as a Wnt agonist in certain tumour tissues and that it can be a Wnt agonist or antagonist at different tissue concentrations." (PMID 27685706, 2016). "The prospective LS series indicated significantly higher frequencies of hypermethylation for SFRP1 (95 %, p = 0.006) and SFRP2 (67 %, p = 0.012) in carcinomas vs. normal colonic mucosa." (PMID 26203307, 2015). "These conflicting observations regarding SFRP2 promoter methylation indicate epigenetic as well as genetic heterogeneity that is characteristic of all cancers in general including HCC." (PMID 24947038, 2014). "This study demonstrated that in HCV infected liver tissues hypermethylation at promoter regions of key cancer related genes SFRP2 and DKK1, appears early at CH and LC stages, long before the appearance of HCC." (PMID 24947038, 2014).
cancer (continued). "As a major gene involved in Wnt signaling pathway, SFRP2 (Secreted frizzled related protein 2, OMIM # 604157), is a key Frizzled regulator associated with a wide range of developmental and disease processes such as cancer, inflammation and fibrosis." (PMID 24386373, 2013). "Many of the differentially expressed genes are implicated in tumorigenesis, and 5 of the upregulated genes are involved in the WNT pathway (e.g. Fst, Lgr5, Sfrp1, Sfrp2, and Wisp2), which is dysregulated in a variety of cancers." (PMID 20429939, 2010). "SFRP2 promoter methylation was detected in 165/199 primary carcinomas (83%) whereas all cancer-related and unrelated normal breast tissues were not affected by SFRP2 methylation." (PMID 18990230, 2008). "Most studies consider SFRP2 a tumor suppressor gene, although a few studies have suggested that SFRP2 may have a cancer-promoting effect on certain cancer types." (PMID 39729237, 2025). "However, the role of SFRP2 in cancer cells is multifaceted and likely contingent upon the specific cellular environment and context." (PMID 38802858, 2024). "Additionally, there are few studies concerning the use of recombinant human SFRP2 (rhSFRP2) in cancer research, emphasizing the urgency of exploring its potential as a therapeutic target." (PMID 38802858, 2024). "Our findings revealed that SFRP2 promoter methylation in whole blood could predict cancer stage (I + II vs. III + IV) (AUC = 0.653), lymph node invasion (AUC = 0.692), and CRC recurrence (AUC = 0.699) in patients with CRC (all with p < 0.05)." (PMID 38802858, 2024). "While SFRP2 methylation in stool samples can be useful for cancer diagnosis, SFRP2 methylation in blood samples may serve as a prognostic factor." (PMID 38802858, 2024). "Our study underwent cross-validation with other studies highlighting the role of SFRP2 in cancers and may lead to more significant findings." (PMID 38069266, 2023). "Osteomimicry is a key element of cancer cell survival during early metastasis, and SFRP2 may be one of the crucial molecular players that modulates cancer cells and their environment to increase their adaptation to evade the immune response." (PMID 36552843, 2022). "SFRP2 expression is downregulated in cancer cells by promoter hypermethylation." (PMID 35892888, 2022). "Likewise, due to its interaction with the fibronectin–integrin complex, SFRP2 can increase cell adhesion, which is an essential prerequisite for cancer cells to survive in the metastatic bone niche." (PMID 36552843, 2022). "Moreover, SFRP2 overexpression reduced the expression levels of cancer stemness markers such as Oct4, Lin28, Nanog, and Sox2." (PMID 34852024, 2021). "Importantly, they did not observe any weight loss or pathological abnormalities in mice treated with these antibodies, suggesting that targeting SFRP2 is a safe anti-cancer strategy." (PMID 33140138, 2021). "Therefore, targeting of SFRP2 with anti-SFRP2 antibodies or small molecules can disrupt this process, making it a promising approach in anti-cancer therapy." (PMID 33140138, 2021). "In addition, recent studies have revealed that overexpression of sFRP2 can promote the invasive, metastatic, and therapeutic resistance potential of certain types of cancer." (PMID 30944668, 2019). "Previous studies have revealed that sFRP2 is dysregulated in many types of cancer." (PMID 30944668, 2019). "However, under certain circumstances, SFRP2 has been shown to display a synergistic effect on Wnt/β-catenin signaling, functioning as an active agonist of Wnt16b, facilitating cancer cell proliferation, migration and drug resistance." (PMID 28794794, 2017). "Moreover, SFRP1 and SFRP2 expressions were significantly lower in the untreated cancer cell lines compared to the corresponding normal controls (data not shown)." (PMID 26203307, 2015). "Similarly, the methylation of SFRP1/2/4/5 was also present in normal control samples, although SFRP2 showed the highest cancer specificity among the SFRP genes." (PMID 25487617, 2015).
cancer (continued). "As previously reported, the expression of SFRP2 was down-regulated by methylation in cancer." (PMID 25370898, 2014). "We found that SFRP2 was detected in 67% of serum samples of cancer patients." (PMID 17848950, 2007). "Therefore, while there are discrepancies in SFRP expression likely arising because of the heterogeneity of DNA methylation in PCa, our results demonstrate a link between elevated SFRP2 expression and cancer progression, particularly in PCa, emphasizing the role of SFRP2 in disease progression." (PMID 37965470, 2023). "Thus, the Wnt pathway, and specifically SFRP2, might show great promise as target for anti-cancer therapy in dogs with PPGL." (PMID 37691636, 2023). "Indeed a pan-cancer, in silico study suggests that despite their proposed roles as Wnt antagonists SFRP2 and SFRP4 may promote processes such as cellular invasion and metastasis." (PMID 33277667, 2021). "However, the contribution of sFRP2 to the biology of cancers remains controversial." (PMID 30944668, 2019). "A number of SASP components including WNT16B, SFRP2, SPINK1, and AREG display strong capacity in conferring resistance to cancer cells." (PMID 37475161, 2024). "Thus, SFRP2 may be an important gene with promising research prospects in pan-cancer." (PMID 38069266, 2023). "It has been reported that SFRP2 and SFRP4 levels are tightly correlated with each other, which shares a common gene program across multiple cancers." (PMID 35372028, 2022). "SFRP1, SFRP2, and SFRP5 were significantly correlated with the clinical cancer stage in GC patients." (PMID 34205081, 2021). "Upregulation of SFRP2 and TLE4 suggests transcriptional inactivation of Wnt/β-catenin signaling, which leads to the suppression of cancer stemness and EMT40–42." (PMID 33270844, 2020). "As expected, many apoptosis-related genes, involving ARHGEF2, TNFRSF12A, and SFRP2, were hypermethylated in CMT, and some oncogenes in human cancers, HRAS, FAM83H, and RET, were found as hypomethylated." (PMID 31569550, 2019). "Recently, we disclosed the remarkable potential of a damaged TME in conferring resistance to cancer cells that survive anticancer therapies, as exemplified by the SASP factors including WNT16B and SFRP2." (PMID 31493351, 2019). "Top five up-regulated genes in malignant tumours were COL11A1, SFRP2, LCN2, COL2A1 and H19, while top up-regulated genes in benign tumours were MMP3, MMP1, AREG, PTHLH and SFRP2." (PMID 30517191, 2018). "First, four out of 16 representative DEGs found in all three subtypes of canine MGTs have strong references in human cancer as biomarkers: CCL23, CXCL10, SFRP2, and FRZB." (PMID 30205506, 2018). "Compared to surrounding normal colonic crypts, the methylation levels of SFRP1, SFRP2, SFRP5, DKK2, DKK3, mir34b/c, and RASSF1A in MSS CRCs were significantly higher in cancer crypts." (PMID 28533824, 2017). "According to the importance of SFRP2 and MGMT role in cancer progression, promoter methylation of these two genes was investigated in HCT 116 treated with CPUK02." (PMID 28090275, 2017). "Recently, many epigenetic biomarkers have been studied in cancer diagnosis, including hMLH1, E-cadherin, CDKN2A, CDKN2B and APC in GC and SEPT9, SFRP2, THBD, SDC2, VIM and FBN1 in CRC." (PMID 29137404, 2017). "We examined DNA methylation levels of SFRP1, SFRP2, SFRP5, DKK2, DKK3, mir34b/c, RASSF1A, IGFBP7, CDKN2A, and MLH1 in cancerous glands and normal crypts isolated from cancer tissue and the surrounding normal mucosa." (PMID 28533824, 2017). "These 58 predicted target mRNAs included many genes previously reported to be involved in tumorigenesis of CRC or other malignant tumors such as KLF4, SFRP1, SFRP2, RNF138." (PMID 22703586, 2012).